HK2 (hexokinase 2)
Diseases named in the same sentence as HK2 in open-access papers (continued):
Sharing a sentence is not in itself a finding about the gene and the disease.
cancer (continued). "Hexokinase 2 (HK2), which catalyzes the first committed step in glucose metabolism, is induced in cancer cells." (PMID 35173161, 2022). "In particular, c-MYC and HIF-1α promote the expression of glycolytic enzymes hexokinase 2 (HK2), phosphofructokinase 1 (PFK1), triosephosphate isomerase 1 (TPI1), lactate dehydrogenase A (LDHA) in cancer." (PMID 36313705, 2022). "In most cancers, HK1 and HK2 have the highest affinity for glucose transporters and are thought to play important roles in the regulation of antitumor efficacy and tumor prognosis." (PMID 36276846, 2022). "In many types of cancers, c-Myc is always activated and plays key role in reprogramming glycolytic metabolism by activating its target genes, like GLUT1, HK2, PKM2 and LDHA, and then results in cancer cell proliferation, migration and metastasis." (PMID 35689245, 2022). "Notably, G6P mimetics could be used to target HK2 glycolytic activity for cancer therapy." (PMID 35173161, 2022). "HNK reduced the expression of HIF-1α, GLUT1, HK2 and PDK1, decreased ECAR, increased OCR, and decreased glucose uptake, lactate production and ATP production in cancer cells." (PMID 35350760, 2022). "Through the upregulation of GLUTs, PKM2, and HK2, the PI3K-Akt pathway promotes cancer development by facilitating certain cell events such as glycolysis." (PMID 36276846, 2022). "Hexokinase 2 (HK2) and pyruvate kinase (PK), which mediate the first and the last step in glycolysis, respectively, are often up-regulated in cancer cells." (PMID 35897809, 2022). "Hexokinase 2 (HK2), a kinase enzyme involved in glucose metabolism, is prompted in cancer cells and contributes to metastasis." (PMID 36289931, 2022). "Especially, the roles of hexokinase 2 (HK2), lactate dehydrogenase A (LDHA), and pyruvate dehydrogenase kinase 1 (PDK1) have been extensively studied in various cancers." (PMID 35403278, 2022). "In this study, statistically significant overexpression of glycolytic genes HK2, PFKM, and PKM2 was observed in advanced cancer stages." (PMID 35328104, 2022). "GLUT1, HK2, TGK1, and LDHA are key components of the glycolysis pathway and play key roles in cancer metabolism, suggesting that mTORC1-NEAT1 signaling regulates glucose metabolism." (PMID 35547764, 2022). "Moreover, we also demonstrated that circ_0008068 silencing could suppress glycolysis, a glycometabolism that was preferentially adopted by cancer cells to produce more energy for their sustaining growth, by decreasing glycolytic enzyme HK2 and lactate production in OSCC cells." (PMID 35635053, 2022). "Briefly, all three RCC cancer cell lines OSRC, ACHN, and 786-O showed higher levels of HK2 mRNA expression when compared with expression in normal cell line HK-2." (PMID 35265223, 2022). "These genes play keys roles in the cancer metabolism, for example, ODC in the polyamine synthesis and HK2 in the glycolysis." (PMID 36371321, 2022). "Conclusively, collective expression of all three rate limiting glycolytic genes (HK2, PFKM, and PKM2) as novel cancer metabolic biomarkers can be beneficial for predicting disease aggressiveness and diagnosis." (PMID 35328104, 2022). "In the current study, we demonstrate that as a transcriptional activator, SPI1 enriches on promoter regions of glycolytic enzymes HK2 and PGK1 and facilitates their expression in cancer cells." (PMID 34841706, 2021). "Specifically, inhibitors with targets related to glycolysis including hexokinase 2 (HK2) and lactate dehydrogenase A (LDHA) are useful in selectively killing cancer cells." (PMID 35004842, 2021). "Hexokinase 2 (HK2), the first enzyme in the glycolytic pathway, is highly related to cancer progression." (PMID 35006464, 2021). "Here, we silenced HK2 and NR5A2 alone or in combination in SCC-9 cells and found that knockdown of HK2 or NR5A2 suppressed cancer cell growth." (PMID 34277436, 2021).
cancer (continued). "The upregulation of PKM2 expression, which is often associated with increased glycolytic enzymes or glucose transporters (e.g., HK2, GLUT), was described at tissue level in various cancers (e.g., in breast, lung, ovarian, bladder, colon cancers)." (PMID 35029792, 2021). "Investigation of the Oncomine database discovered that HK2 was highly expressed in 8 types of cancer, and investigation of the TIMER discovered that HK2 was highly expressed in 11 types of cancer." (PMID 34708035, 2021). "By disrupting the stability of HK2 mRNA, TTP alters the extracellular acidification rate, oxygen consumption rate, and ATP levels of cancer cells, suggesting that TTP is a negative regulator of HK2 expression and glucose metabolism." (PMID 34026612, 2021). "The levels of HK2, PFK, PKM2, and LDHA have been individually reported to be correlated with cancer cell growth." (PMID 33628847, 2021). "Compared with the three hexokinase isozymes, HK1, HK2, and HK4, the role and mechanism of action of HK3 in cancer is less reported." (PMID 33980323, 2021). "Hexokinase 2 (HK2) is the key rate-limiting enzyme in glycolysis and is overexpressed in NSCLC tumors and promotes cancer cell proliferation." (PMID 33763378, 2021). "Abnormally stimulated HIF-1 functioning as a transcription factor inhibits mitochondrial activity and promotes glycolysis and cancer cell growth by facilitating the expression of glycolysis transporters and key enzymes such as GLUT1, HK2, FBP, PKM2, and LDHA." (PMID 34540667, 2021). "OLD and 6 drugs downregulated GLS1 and HK2, two targets of the drugs schemes, as well as CPT1C, a regulator of fatty acids transport into mitochondria for β-oxidation and of cancer cell senescence through metabolic reprogramming." (PMID 33664364, 2021). "We blocked the tumor anabolism with orlistat, lonidamine and DON (6-Diazo-5-oxo-L-norleucine) (OLD drug scheme) to inhibit FASN, HK2 and GLS, respectively, whereas with the combination of anti-catabolic drugs we aimed to ameliorate cancer cachexia." (PMID 33664364, 2021). "Several important glycolytic regulators including hexokinase 2 (HK2), pyruvate kinase M2 (PKM2), and lactate dehydrogenase A (LDHA), have been proved to be upregulated in the cancer cells." (PMID 33572615, 2021). "Transcription factor SPI1 promotes aerobic glycolysis via upregulating HK2 and PGK1 in cancer cells." (PMID 34841706, 2021). "GBM tumors displayed distinct Warburg-like genetic features, with increased HK2, PGAM1, ALDOC, and PGK1 expression that facilitates lactate production and confers resistance to hypoxic stress in cancer cells." (PMID 35004842, 2021). "Several glycolysis-related proteins, for example, GLUT1, HK2, and LDHA, are often upregulated in several types of cancer, which are related to the Warburg effect and cancer progression." (PMID 34575112, 2021). "In cancer cells, GLUT1, HK2, PKM2, LDHA, MCT4, and other glycolysis-related proteins directly affect the glycolytic process." (PMID 33356727, 2021). "Interestingly, LDHB and HK2 are localized to the inner and outer mitochondrial membrane, respectively, and there may be a link between their expression and mitochondrial apoptosis in cancer cells." (PMID 33849427, 2021). "Our results revealed that the expression of CK-18 and E-cadherin were downregulated, and the expression of genes related to EMT induction and cancer aggressiveness, including Twist, Snail, SOX2 and Vimentin, were upregulated upon HK2 overexpression." (PMID 34174908, 2021). "Further investigation demonstrated that depletion of HK2 activated AMPK to subsequently inhibit mTORC1 activity, which plays a sensor role in cancer metabolism." (PMID 32083006, 2020). "Targeting HK2/VDAC interaction thus represents a promising approach to overcome drug resistance and inducing apoptosis in cancer cells." (PMID 32806533, 2020).
cancer (continued). "HK2 is highly expressed in various cancers, which binds with the VDAC on the outer mitochondria, enhances aerobic glycolysis and resists apoptosis of cancer cells." (PMID 33143000, 2020). "MYC invariably promotes expression of critical enzymes involved in aerobic glycolysis, such as HK2 and LDHA, making cancer cells more vulnerable to glycolysis inhibition." (PMID 32651356, 2020). "Further, RASSF1A overexpression augmented HIF-1α promoter occupancy and transactivation of PDK1, HK2 and LDHA in both smooth muscle cells and cancer cells." (PMID 31086178, 2019). "Even though increasing evidences have shown that the critical glycolytic enzymes, including HK2, PKM2 and LDHA, play important roles in cancer development, the drugs against these enzymes are far from clinical application." (PMID 31431517, 2019). "Moreover, HK2 itself could be a therapeutic target in cancer therapy." (PMID 31718692, 2019). "Matrine inhibits the mRNA and protein expression of HIF-1α, thereby suppressing the transcription of GLUT1, HK2, and LDHA, the downstream targets of HIF-1, which are the key enzymes involved in the glycolytic energy metabolism of cancer cells." (PMID 31849679, 2019). "HK2 protein expression was most strongly detected, whereas ENO2 protein expression barely observed in both normal and cancer tissues." (PMID 31428701, 2019). "Dysfunction of glycolytic enzymes, such as HK2 and PKM2, is closely correlated with the glucose metabolic reprogramming in human cancer cells." (PMID 31595166, 2019). "Cancer cells predominantly express SLC2A1 (GLUT1) and SLC2A3 (GLUT3) to transport glucose across the cell membrane and Hexokinase 1 and Hexokinase 2 to phosphorylate glucose." (PMID 31784510, 2019). "The CRISPR Cas9 method was used to establish isogenic HK1+HK2+ and HK1−HK2+ cell lines to evaluate HK1−HK2+ cancer cell sensitivity to the combination therapy." (PMID 29988332, 2018). "In this study, we describe a triple-combination therapy for treatment of HK1−HK2+ cancers that targets the HK1−HK2+ cancer-specific modes of energy generation, HK2-driven glycolysis, mitochondrial oxidative phosphorylation, and fatty acid oxidation." (PMID 29988332, 2018). "Targeting HK2-mediated glycolysis, mitochondrial respiration, and fatty acid oxidation in liver HK1−HK2+ cancer cells results in a synergistic decrease in cancer energy/ATP production." (PMID 29988332, 2018). "HIF-1α induces the over-expression of several glycolytic proteins including glucose transporters (i.e., GLUT1 and GLUT3), and enzymes such as hexokinase-1 (HK1), HK2 and LDHA in cancer cells." (PMID 30619850, 2018). "Previous research has found that overexpression of HK2 and PKM2 governs the glucose influx and sustain high levels of glycolysis to promote cancer cell migration and induce stem cell differentiation." (PMID 29954422, 2018). "Cancer cells up-regulate the rate-limiting enzymes of glycolysis such as GLUT1, HK2, PKM2, and LDHA as a result of the expression of oncogenes including RAS, SRC, or EGFR." (PMID 29559564, 2018). "When we partially inhibited HK2-driven glycolysis and OXPHOS in HK1−HK2+ cancer cells, we observed that FAO was upregulated as indicated by ACC phosphorylation and disappearance of intracellular lipid droplets." (PMID 29988332, 2018). "Numerous glycolytic enzymes such as HK-2, PFK2, PKM2, LDHA, and PDK, have been reported to be rate-limiting factors that are dysregulated in various types of cancer." (PMID 30602670, 2018). "Thus, HK2 could represent an ideal cancer-specific target for HCC therapy." (PMID 29386513, 2018). "Among the genes with the strongest reduction in expression we found hexokinase 2 (HK2) and glutaminase (GLS), which were both reported to be essential for energy generation to support proliferation in different cancer types." (PMID 28201987, 2017). "We show that knockdown of HK2 results in decreased PDAC growth in vitro and in vivo, in agreement with what has been observed in other cancers." (PMID 28915575, 2017).
cancer (continued). "The gene expression of HK2 and PFK in various cancer cell lines was higher than that of LO2, but their protein expression is lower except LM3 and BEL-7402." (PMID 28498814, 2017). "This work also summarizes two key discoveries, one of which relates to hexokinase-2 (HK2), a major player in both the “Warburg effect” and cancer cell immortalization." (PMID 27983708, 2016). "Several potential candidates that are overexpressed in certain cancer types include PKM2, GLUT1, HK2, PHGDH and LDH-A." (PMID 27385092, 2016). "Myc and HIF1A are the best-known transcriptional regulators controlling expression of glycolysis genes, such as GLUT1, HK2, PDK1, and LDHA, whose expression levels are highly elevated in cancer cells." (PMID 26989077, 2016). "For example, hexokinase 2 isoform (HK2), which catalyzes the rate-limiting first step of glycolysis, plays a key role for the Warburg effect in cancer." (PMID 28040803, 2016). "Upon the activation of AKT, HK2 undergoes translocation to the outer membrane of mitochondria, leading to a metabolism shift from OXPHOS to glycolysis, thus promoting cancer cell survival under metabolic stress." (PMID 26565812, 2016). "Among the various enzymes and isozymes that catalyze specific reactions in glycolysis, four crucial speed-limiting enzymes, GLUT1, HK2, PKM2, and LDHA favor aerobic glycolysis and growth in certain cancer types." (PMID 26512921, 2015). "This form of HK is also known as hexokinase-2 (HK2) and has been found to be preferentially expressed in various cancers." (PMID 26437434, 2015). "The higher affinity of mitochondrial HK2 for glucose, ATP, and VDAC1 represents a high advantage for cancer cells survival and growth, conferring to them an aerobic glycolytic phenotype underlying the Warburg effect." (PMID 24648844, 2014). "MYC is frequently altered in human cancer and has been reported to regulate many glucose metabolism genes, such as glucose transporter GLUT1 and hexokinase 2 (HK2)." (PMID 24884974, 2014). "Of the many subtypes of glucose transporters and hexokinases, the GLUT1 subtype is considered to be the glucose transporter mainly upregulated in cancer cells and HK1 and HK2 are the hexokinase subtypes most frequently found overexpressed in cancer cells." (PMID 26824929, 2013). "Hexokinase-2 (HK2) and more recently choline kinase alpha (CKA) expression has been correlated with clinical outcomes in several major cancers." (PMID 23071593, 2012). "Altered expression of glucose transporters (GLUTs) and metabolic enzymes such as pyruvate kinase (PK), hexokinase II (HK2), lactate dehydrogenase (LDH), pyruvate dehydrogenase kinase (PDK) have been demonstrated in various cancers including GBMs." (PMID 24213470, 2012). "Lonidamine (LON) (1-[(2,4-Dichlorophenyl)methyl]-1H-indazole-3-carboxylic acid) is a hexokinase 2 inhibitor that has been shown to induce apoptosis and treat MDR in various cancer cell lines." (PMID 21931642, 2011). "This family harbours several genes aberrantly expressed in various cancers as well as established (PSA/hK3, hK2) and potential (hK6, hK10) cancer markers." (PMID 12439719, 2002). "Simultaneous overexpression of non-canonical glycolytic isoforms, such as HK2, a well-known marker of cancer metabolism, also showed differential expression." (PMID 41009047, 2025). "Moreover, MAO inhibitors impaired cancer cell glucose metabolism by decreasing the expression of glucose transporter 1 (GLUT1) and hexokinase 2 (HK2) with reduced glycolysis and oxidative phosphorylation in conjunction with pyruvate depletion." (PMID 39714760, 2025). "Interestingly, central carbon metabolism in cancer (HK2, MAPK3, MYC, PFKP, PKM2, SLC16A3), galactose metabolism (B4GALT2, HK2, PFKP) and fructose and mannose metabolism (HK2, PFKFB4, PFKP) are associated with metabolism." (PMID 39924557, 2025).
cancer (continued). "In cancer cells, higher levels of c-Myc expression drives increased transcription and activity of key glycolytic enzymes, including lactate dehydrogenase (LDH) and hexokinase 2 (HK2)." (PMID 41586225, 2025). "Similarly, in other cancers, lncRNA MBNL1-AS1 (muscle blind-like protein 1 antisense RNA 1) confers HCC resistance to tripterine through the lncRNA MEBNL-AS1/miR-708-5p/HK2 axis." (PMID 40264038, 2025). "In a model of KRAS-driven lung cancer, HK2 is transcriptionally activated by the transcription factor BACH1, which is stabilized by antioxidant treatment, triggering metastatic spread favored by glycolytic metabolism in cancer cells." (PMID 40734168, 2025). "Key enzymes such as hexokinase 2 (HK2), pyruvate kinase M1/2 (PKM), and acetyl-CoA carboxylase alpha (ACACA) were highlighted, reflecting the metabolic reprogramming often observed in cancer cells, known as the Warburg effect." (PMID 40678800, 2025). "Notably, studies have shown that neutralizing IL6 or IL6R antibodies can reduce CAF-induced expression of HK2, emphasizing the important role of IL6 in promoting cancer cell growth." (PMID 40427188, 2025). "There was also a reduction in HK2 and mTORC1 expression and an increase in oxygen consumption, which mirrors the previous findings regarding AMPK activation and suggests improvement from the Warburg effect shift of cancer cells." (PMID 39955067, 2025). "Although the role of HK2 in tumorigenesis has been attributed to its glycolytic activity, HK2 has also been shown to execute noncanonical functions that often regulate processes that are highly relevant for cell transformation and cancer development." (PMID 40956859, 2025). "HK2 expression is absent or low in most normal adult cells, while it is highly expressed in cancer cells." (PMID 40612109, 2025). "In cancer glycolysis, three enzymes have been identified as the rate‐limiting enzymes, including Pyruvate Kinase Type M2 (PKM2), Phosphofructokinase‐1 (PFK1), and Hexokinase 2 (HK2)." (PMID 41476787, 2025). "For example, excessive activation of CMA of hexokinase 2 (HK2, a key enzyme in glucose metabolism) can lead to metabolic disorder of cancer cells and trigger metabolic catastrophe, resulting in the death of cancer cells." (PMID 40083922, 2025). "In addition, a new mechanism for inhibition of HCC growth by LA-CMGL was demonstrated: specifically, miR-145 sensitizes cancer cells to CPT and promotes apoptosis by targeting the SENP1-mediated HK2 SUMOylation and glycolysis pathways." (PMID 39215325, 2024). "Targeting key components of glycolysis, such as hexokinase 2 (HK2) and lactate dehydrogenase A (LDHA), with inhibitors could potentially selectively eliminate cancer cells." (PMID 38479191, 2024). "In support of this approach, deleting HK2 can decrease cancer cell proliferation without prominent side effects in animal models, suggesting HK2 is a promising target for cancer therapy." (PMID 39192292, 2024). "HK2, PFKFB3, and PKM2 have been identified as key glycolysis enzymes that participate in glucose metabolism; they can enhance glucose uptake and lactate production, thereby providing a source of energy for cancer cells." (PMID 39684424, 2024). "Mechanistically, miR-145 may sensitize cancer cells to CPT and promote apoptosis by targeting SENP1-mediated HK2 SUMOylation and glycolysis pathways." (PMID 39215325, 2024). "In the future, the binding of HK2 and HKDC1 could be specifically targeted as a promising therapeutic strategy for effective outcomes in cancer." (PMID 37109475, 2023). "Besides, Wnt signaling up-regulated LDHA,HK2 and PKM2 to enhance glycolysis in cancer cells and bone marrow mesenchymal stem cells (BM-MSCs) activated Wnt signaling in tumors via targeting SFRP1 due to the delivery of BM-MSC-derived exosome miR-1180." (PMID 37208722, 2023).